SMIM9 (small integral membrane protein 9)
Synonyms: CXorf68
Tractability: Antibody: UniProt places it where antibodies can reach, with high confidence; UniProt predicts a signal peptide or a membrane-spanning region; its Gene Ontology location is reachable by antibodies, with medium confidence.
Gene: Protein-coding gene on chromosome X (154,823,348 to 154,834,662, reverse strand). Ensembl gene ENSG00000203870.
Subcellular location: Cell membrane
Gene Ontology:
Cellular component: plasma membrane
Homologues: Orthologues: chimpanzee SMIM9 (97% identical), macaque SMIM9 (95% identical), pig SMIM9 (60% identical), mouse Smim9 (41% identical).
Diseases named in the same sentence as SMIM9 in open-access papers:
SMIM9 is named in the same sentence as 1 disease in open-access papers, as found by Europe PMC text mining. Sharing a sentence is not in itself a finding about the gene and the disease.
SMIM9 shares sentences with these, for which no sentence is quoted: Duodenal stenosis (1 paper).